NOX3 (NADPH oxidase 3)
Diseases named in the same sentence as NOX3 in open-access papers (continued):
Sharing a sentence is not in itself a finding about the gene and the disease.
osteoarthritis (1 paper, 2019). A noninflammatory degenerative joint disease occurring chiefly in older persons, characterized by degeneration of the articular cartilage, hypertrophy of bone at the margins and changes in the synovial membrane. "Osteoarthritis mapped to a long intergenic region on chromosome 1, between genes encoding for NADPH oxidase 3 (NOX3), an intriguing candidate for articular cartilage degradation, and AT-rich interactive domain 1B (ARID1B) that has been previously linked to joint laxity." (PMID 31881848, 2019).
pancreatic cancer (1 paper, 2024). "Treatment of human pancreas cancer cell line (Panc-1) cells with 8-OhdG resulted in decreased total cellular ROS production and a reduction of Nox1, Nox2 and Nox3 mRNA expression." (PMID 38397817, 2024).
prostate carcinoma (1 paper, 2017). A carcinoma that arises from epithelial cells of the prostate gland. "Although the information on NOX3 expression in prostate cancer is scarce, studies have shown that NOX3 has limited or no pathological significance in prostate cancer." (PMID 29065504, 2017).
pulmonary hypertension (1 paper, 2018). Increased pressure within the pulmonary circulation due to lung or heart disorder. "The results suggested that rs6557421 variant in Nox3 and rs3744439 variant in Tbx4 might have potential effect on individual susceptibility to pulmonary hypertension, which could lead to therapeutic or diagnosis approaches in PH." (PMID 30290780, 2018). "In summary, it is biologically plausible that rs6557421 variant in Nox3 and rs3744439 variant in Tbx4 may have potential effects on individual susceptibility to pulmonary hypertension, which could lead to therapeutic or diagnosis approaches in PH." (PMID 30290780, 2018).
type 2 diabetes (1 paper, 2023). "Correspondingly, the treatment of GLP-1 RAs for one week in rats with type 2 diabetes could reduce NOX3 and SOD2 levels in the retina cells, alleviate autophagy through the GLP-1R-ERK1/2-HDAC6 signaling pathway, and finally improve DR." (PMID 36737746, 2023).
cancer (9 papers, 2011 to 2024). A tumor composed of atypical neoplastic, often pleomorphic cells that invade other tissues. "Although the used cancer cell lines expressed Nox2, Nox3 and Nox4, only Nox3 was recruited to the membrane-located signaling platform, which formed after CD95L treatment." (PMID 38397817, 2024). "The fourth study investigated several cancer cell lines, and these four studies are, so far, the only research conducted for Nox3-derived ROS in the context of signaling pathway modifications." (PMID 38397817, 2024). "Miyano and colleagues firstly showed that Nox3 is expressed and active in innate immune cells, namely the macrophage-like cancer cell line RAW 246.7, which was confirmed in later studies." (PMID 38397817, 2024). "Further screening of various cancer cell lines, however, showed strong Nox3 mRNA and protein expression in the cell lines H28 (mesothelioma), H358 (bronchoalveolar) and A549 (adenocarcinoma)." (PMID 38397817, 2024). "Nevertheless, research was also conducted to develop therapeutic approaches for Nox3-related involvement during diabetes, cancer and MS." (PMID 38397817, 2024). "To better understand how RV induces ROS generation in cancer cells, we investigated if RV treatment has any impact on the expression of Nox1, Nox2, Nox3, Nox4 and Nox5 in NSCLC cells." (PMID 23533664, 2013). "Notably, most of the in vitro studies which addressed Nox3 have used cancer-derived cell lines like HepG2 (as hepatocyte model) or HEI-OI (as an inner ear hair cell model)." (PMID 38397817, 2024). "In co-expression experiments with various cancer cell lines (HeLa, CHO, COS-7), they observed a small p67phox/NOXA1-dependent enhancement of Nox3 activation by Rac." (PMID 38397817, 2024). "Mitochondria and NOXs family, including NOX1, NOX2, NOX3, NOX4, NOX5, DUOX1, and DUOX2, are two important sources of ROS production in cancer cells." (PMID 35418176, 2022). "The SRC proto-oncogene has been demonstrated to activate NADPH oxidases NOX1-, NOX3-, NOX4-, and NOX5-induced O2•− production in cancer models and to increase mutant SOD1 aggregate formation in ALS." (PMID 29478325, 2019). "The data demonstrate stable and low mRNA expression of NOX1, NOX3, NOX4, and NOX5, whereas the expression of NOX2 is markedly higher and variable in different forms of cancer." (PMID 29478325, 2019). "Mitochondria and NADPH oxidases of the Nox family including NOX1, NOX2, NOX3, NOX4, NOX5, DUOX1 and DUOX2, are two important sources of ROS production in cancer cells." (PMID 30755243, 2019). "All of these studies did not investigate ex vivo cells but instead used human cancer cell lines and co-expression approaches to combine the Nox3 core protein and various Nox subunits." (PMID 38397817, 2024). "p22phox is also the functional partner of other NOX isoforms such as NOX1, NOX3 and NOX4, and its lack of expression indicates that ATC cancer cells do not express these NADPH oxidase systems and consequently do not produce superoxide and H2O2 on their own." (PMID 21811634, 2011).
tumor (9 papers, 2017 to 2024). "By immunohistochemistry (IHC) It was observed an increase in caspase-3 and Nox-3 levels and an inhibition of tumor growth after 11 days by tumor mass measurement by a sliding caliper." (PMID 36142145, 2022). "Specifically, EGb significantly decreased gene expression of Nrf2, Cat and Nox3, in the liver of mice with tumors (Tumor, p < 0.05)." (PMID 29197355, 2017). "This is confirmed by the EGb-induced reduction in mRNA expression of TIMP1, Caspase9, Bad, Apaf1, Nrf2, Cat and Nox3 in the Tumor group." (PMID 29197355, 2017). "TWS119 treatment led to a further up-regulation of Nox3 mRNA in the isolated 4T1 tumor cells." (PMID 38397817, 2024). "Besides a reduction of tumor growth, an increase in caspase-3 and apoptosis, as well as NADPH-oxidase 3 (NOX3), was observed in the plasma-treated tumor tissue." (PMID 32708225, 2020). "The NOX family, which includes NOX1, NOX2, NOX3, NOX4, and NOX5 subtypes, is a key mediator of cyclic hypoxia-mediated ROS production and tumor progression." (PMID 36278207, 2022). "Nox3 mRNA was absent in all isolated tumor tissues derived from the colon, liver, lung, kidney, prostate, stomach, ovary, breast, testis and brain." (PMID 38397817, 2024). "Glioblastoma tumour growth was significantly decelerated with CP treatment, with immunohistological analysis showing extensive DNA damage, NOX3 expression (indicating endogenous H2O2 production), and caspase 3 activation, which implicate JNK and p38 activity, but tumour growth still persisted." (PMID 38785562, 2024).
cardiovascular disease (2 papers, 2015 to 2024). "Nevertheless, tremendous research exploited important roles of Nox3 during lung and cardiovascular diseases, again revising the view of Nox3 as “restricted to the inner ear”." (PMID 38397817, 2024). "NOX3 is part of the Nox family of NADPH oxidases, involved in generation of reactive-oxygen species and in the development and progression of cardiovascular disease." (PMID 26284107, 2015).
infection (2 papers, 2021 to 2024). The state of being infected such as from the introduction of a foreign agent such as serum, vaccine, antigenic substance or organism. "Nevertheless, this is so far the one and only study that has described an induction of Nox3 protein expression as response to infection." (PMID 38397817, 2024). "While Nox3 involvement during various body functions and disease progression was intensively investigated (Section 4 and Section 5), this last example dramatically displays the vast gap of knowledge of Nox3 in the context of immunity and infection." (PMID 38397817, 2024). "Both findings suggest a possible role for Nox3 during infection and inflammation." (PMID 38397817, 2024).
retinal disorder (1 paper, 2025). Any disease or disorder of the retina. "Further research is required to elucidate Nox3 function in retinal disorders." (PMID 41339603, 2025). "However, the role of Nox3 in retinal disorders remains entirely unknown." (PMID 41339603, 2025).
NOX3 also shares sentences with these, for which no sentence is quoted: age-related hearing loss (2 papers); asthma (2); deafness (2); Abdominal obesity (1); adenocarcinoma (1); Hearing impairment (1); Hip dysplasia (1); hyperlipidemia (1); Hyperoxaluria (1); metabolic syndrome (1); multiple sclerosis (1); nevus (1); noise induced hearing loss (1); relapsing-remitting multiple sclerosis (1); thyroid cancer (1).